KLK8 (kallikrein related peptidase 8)
Diseases named in the same sentence as KLK8 in open-access papers (continued):
Sharing a sentence is not in itself a finding about the gene and the disease.
adenoma (1 paper, 2021). A neoplasm arising from the epithelium. "Moreover, the expression of KLK8 increased gradually in normal colon tissue, adenoma and metastatic adenocarcinoma." (PMID 34552064, 2021).
amyloid (1 paper, 2019). "In accordance with our finding, a positive association between KLK8 levels and amyloid load was detected in the hippocampus only in early disease stages of AD mice, when inhibition of KLK8 led to increased amyloid clearance, but not in the further course of the disease." (PMID 31467673, 2019).
anxiety disorder (1 paper, 2021). A category of psychiatric disorders which are characterized by anxious feelings or fear often accompanied by physical symptoms associated with anxiety. "The KLK8-mediated cleavage of neuregulin-1, synaptic adhesion molecule L1, and ephrin type-B receptor 2 has been implicated in the regulation of hippocampal neural plasticity and the pathogenesis of anxiety disorders 68-70." (PMID 33754057, 2021).
astrocytoma (1 paper, 2015). "Like KLK6, higher levels of KLK1, KLK7, KLK8, KLK9 and KLK10 were all found to be associated with higher astrocytoma grade." (PMID 26231762, 2015). "In this study we determined KLK1, KLK6, KLK7, KLK8, KLK9 and KLK10 protein expression in two independent tissue microarrays containing 60 grade IV and 8 grade III astrocytoma samples." (PMID 26231762, 2015). "Expression of KLK1, KLK6, KLK7, KLK8, KLK9 and KLK10 protein was assessed by immunohistochemical analysis of grade III (n = 8) and grade IV (n = 60, n = 55 for KLK1) astrocytoma samples." (PMID 26231762, 2015).
autism (1 paper, 2020). Persistent deficits in social interaction and communication and interaction as well as a markedly restricted repertoire of activity and interest as well as repetitive patterns of behavior. "People who have structural genetic variants of KLK8 can suffer mental illnesses such as intellectual and learning disabilities, seizures, and autism." (PMID 32655372, 2020). "Individuals carrying structural genetic variants encompassing KLK8, manifest mental illness such as intellectual and learning disabilities, seizures, and autism." (PMID 32655372, 2020).
Cognitive impairment (1 paper, 2020). Abnormal cognition is characterized by deficits in thinking, reasoning, or remembering. "Interestingly, KLK8 expression measured in blood as well as cerebrospinal fluid is a promising early biomarker for AD as well as mild cognitive impairment due to AD." (PMID 32414324, 2020).
dementia (1 paper, 2025). Loss of intellectual abilities interfering with an individual's social and occupational functions. "We particularly underscored that DFX is a preferential inhibitor of KLK8, a relevant serine protease in AD, dementias, and other psychiatric disorders, although its selectivity toward trypsin‐like KLKs remains to be optimized." (PMID 40192482, 2025).
diabetic cardiomyopathy (1 paper, 2021). Diabetic cardiomyopathy is a disorder of the heart muscle in people with diabetes. "Using both KLK8 knockout mice and KLK8 transgenic rats, the present study investigated the precise role of KLK8 in mediating diabetic cardiomyopathy and demonstrated that upregulation of KLK8 contributes to the development of EndMT and diabetic cardiac fibrosis." (PMID 33754057, 2021).
endometrial cancer (1 paper, 2023). Primary or metastatic malignant neoplasm involving the endometrium (mucous membrane that lines the endometrial cavity). "Kallikrein-related peptidase 8 (KLK8) is one such protein that has been identified to be highly expressed in cervical, ovarian and endometrial cancers, indicating that it could be a viable target for therapy." (PMID 36905477, 2023).
endothelial dysfunction (1 paper, 2021). In vascular diseases, endothelial dysfunction is a systemic pathological state of the endothelium (the inner lining of blood vessels) and can be broadly defined as an imbalance between vasodilating and vasoconstricting substances produced by (or acting on) the endothelium. "The present study next explored whether upregulation of KLK8 contributes to high glucose-induced endothelial dysfunction and EndMT using an in vitro model." (PMID 33754057, 2021).
epilepsy (1 paper, 2018). A brain disorder characterized by episodes of abnormally increased neuronal discharge resulting in transient episodes of sensory or motor neurological dysfunction, or psychic dysfunction. "Neuropsin (KLK8) downregulation has been reported to be associated with seizure burden in animal model of kainate-induced epilepsy." (PMID 30298130, 2018).
gastric cancer (1 paper, 2025). A primary or metastatic malignant neoplasm involving the stomach. "Lowering the extracellular pH below 6.5 in turn may increase KLK8 expression and secretion, as shown in gastric cancer cells." (PMID 40064965, 2025).
mental disorder (1 paper, 2020). A disease that has its basis in the disruption of mental process. "It is, thus, possible that KLK8 blood parameters levels may accordingly serve as diagnostic biomarkers in mental disorders." (PMID 32414324, 2020).
multiple sclerosis (1 paper, 2020). A progressive autoimmune disorder affecting the central nervous system resulting in demyelination. "Interestingly, at the date, the possible role or differential regulation/function of KLK8 and/or KLK6 in multiple sclerosis or other neural diseases associated with viral infections remains to be elucidated." (PMID 32655372, 2020).
ovarian tumors (1 paper, 2020). "In ovarian tumors, the expression of the KLK8 and its spliced variants indicate the frequent expression of novel variants." (PMID 33150763, 2020).
pancreatic neuroendocrine tumor (1 paper, 2021). Pancreatic endocrine tumor, also known as pancreatic neuroendocrine tumor (PNET), describes a group of endocrine tumors originating in the pancreas that are usually indolent and benign, but may have the potential to be malignant. "Notably, there are 8 pancreatic neuroendocrine tumor (NET) samples in the TCGA-PAAD database, which exhibit low KLK8 expression." (PMID 34395235, 2021).
Parkinson disease (1 paper, 2020). A progressive degenerative disorder of the central nervous system characterized by loss of dopamine producing neurons in the substantia nigra and the presence of Lewy bodies in the substantia nigra and locus coeruleus. "The dysregulation of certain KLKs, that is, KLK1 and KLK7, but mainly KLK6 and KLK8, may contribute to the development of neurodegenerative or neurological disorders such as Alzheimer’s and Parkinson’s diseases, memory disorders or mental illness." (PMID 32655372, 2020).
progeria (1 paper, 2026). "Additionally, DEGs were identified in KLK8‐induced senescent MLVECs, senescent endothelial cells from progeria mice, and naturally aged mice." (PMID 41310943, 2026).
serous ovarian cancer (1 paper, 2019). "Therefore, it is not too surprising that we observed indication for coordinate expression of some KLKs such as KLK6/KLK8 (Spearman correlation of mRNA levels: rs = 0.636;), KLK10/KLK11 (rs = 0.647;), or KLK5/KLK7 (rs = 0.568; unpublished results) in advanced high-grade serous ovarian cancer." (PMID 30811511, 2019).
viral infections (1 paper, 2020). "Recent studies have shown the importance of KLK8 during viral infections, such as those produced by the human papillomavirus (HPV)." (PMID 32655372, 2020).
tumor (24 papers, 2011 to 2026). "Based on these observations, we propose that hemicleavage by Klk8 hinders tumor-suppressive Activin-A signaling by interfering with the stepwise proteolytic maturation mediated by furin." (PMID 40064965, 2025). "To evaluate possible mechanisms of how Activin-A cleavage by Klk8 facilitated tumor growth, we first analyzed its impact on tumor-infiltrating CD8+ T cells." (PMID 40064965, 2025). "This suggests that Klk8 promotes tumor growth by locally regulating the flux of differentially processed forms of Activin-A, rather than by increasing the steady-state level of fully mature form." (PMID 40064965, 2025). "To gain insight into KLK8 distribution across tumor types and normal tissues, we analyzed its mRNA and protein expression using public databases." (PMID 40064965, 2025). "Both in vivo studies and clinical data from patients with NSCLC reveal that elevated KLK8 levels correlate with slower tumor growth, reduced invasion, and extended time to postoperative recurrence, particularly in early-stage cases." (PMID 40124684, 2025). "Using multiple public LUSC datasets, we found that Kallikrein-8 (KLK8) expression was higher in tumor samples and was correlated with inferior survival." (PMID 38273291, 2024). "The KLK8 transcript 1 and KLK8 transcript 2 were against tumor cell dissemination, while the KLK8 transcript 4 was on the opposite." (PMID 38273291, 2024). "Imaging analysis and H&E staining of the livers from the group that received KLK8-overexpressing RKO cells also showed greater tumour metastasis than those from the group that received SCH79797 treatment." (PMID 34552064, 2021). "We found that KLK8 was up-regulated in tumor tissues in the TCGA-PAAD cohort, and was an independent prognostic factor for both overall survival and disease-free survival of PDAC." (PMID 34395235, 2021). "Kallikrein-related peptidase 8 (KLK8) acts as an oncogene or anti-oncogene in various tumours, and the abnormal expression of KLK8 is involved in the carcinogenesis of several tumours." (PMID 34552064, 2021). "To further examine the potential relationship between KLK8 and PAAD, we analyzed data from the TCGA-PAAD cohort which was replenished by GTEX database, and found that KLK8 was significantly upregulated in tumor tissues compared to normal tissues (P<0.0001)." (PMID 34395235, 2021). "Although KLK8 and KLK10 overexpression in OSCC and other cancers have been associated with tumor aggressiveness and overall prognosis, their precise mechanisms of activity are yet to be clearly deciphered." (PMID 32630820, 2020). "The mean percent tumor core stained was significantly higher in grade III compared to grade IV for KLK8 (P = 0.0038, Kruskal-Wallis test)." (PMID 26231762, 2015). "The increase in KLK8 expression from BL to W was greatest in women who whose FFTP occurred at a young age, which is consistent with known protective effect of early age at FFTP and a tumor suppressive effect of KLK8." (PMID 22436421, 2012). "Nevertheless, Klk8 shRNAs slowed the growth of βA tumor grafts below that of Ctrl tumors." (PMID 40064965, 2025). "Furthermore, Western blot analysis revealed that compared to shLuc control, both Klk8 shRNAs significantly enriched the tumor lysates for uncleaved A110 relative to A30 at least by the time the tumors reached the endpoint." (PMID 40064965, 2025). "Importantly, Western blot analysis of tumor extracts showed that Klk8 knockdown also significantly decreased the levels of pSmad2 relative to total Smad2." (PMID 40064965, 2025). "Besides elucidating how Activin-A processing is regulated, our findings show that KLK8 holds promise as a target to mitigate Activin-A induced tumor growth." (PMID 40064965, 2025). "In addition, using the xenograft model, the present study found that the tumour volume of the mice in the Lv-KLK8 group was much higher than that of the mice in the Lv-Control group." (PMID 34552064, 2021).
tumor (continued). "KLK8’s potential role in ferritinophagy remains unexplored, but its involvement in extracellular matrix remodeling suggests it may influence iron homeostasis and tumor microenvironment dynamics." (PMID 40124684, 2025). "A previous analysis of the kallikrein-related peptidase family in CRC tumor samples from the TCGA database revealed that KLK6 overexpression in human tumors is associated with the overexpression of other members of the kallikreins protease family, i.e., KLK7, KLK8, and KLK10." (PMID 39594797, 2024). "In summary, we reported the predictive ability and the extensive anti-tumor immunomodulatory capacity of KLK8 in LUSC, suggesting the potentiality of KLK8 as a novel immunoregulatory target in LUSC." (PMID 38273291, 2024). "The analysis of the kallikrein-related peptidase family in CRC tumor samples from The Cancer Genome Atlas (TCGA) database identified a distinct pattern of overexpression of KLK6 along with elevated expression of KLK7, KLK8, and KLK10." (PMID 39594797, 2024). "When the same analyses were done using PEA Oncology II profiling data, 10 proteins correlated to tumor stage (P < 0.05), for example, CD160, TNFRSF4/OX40L, XPNPEP2, SPARC, MAD homolog 5/SMAD5, CPE, hK8/KLK8, WIF‐1, TCL1A, and MIC‐A/B." (PMID 33768639, 2021). "Analysis of tumor extracts and of plasma from tumor-bearing mice revealed that Klk8 knockdown did not overtly decrease Activin-A processing in furin wild-type tumors, or the accumulation of mature Activin-A in plasma of tumor-bearing hosts." (PMID 40064965, 2025). "For patients with low KLK8 expression, they were with a more active TME, which was both observed in the TCGA database and immune marker immunohistochemistry, and they had extensive positive relations with immune cells with tumor-eliminating functions." (PMID 38273291, 2024). "These HLA-A24 ligands were possibly overexpressed in tumor samples and were therefore chosen as nonmutated TAA candidates of CRC111, which comprised peptides encoded by the KLK8, DEFA3, STRIP2, MMP1, FSCN1, TBX15, and PHLDA1 genes." (PMID 34185709, 2021). "Importantly, induction of either of the two Klk8 shRNAs by IPTG nevertheless further diminished tumor growth specifically in B16F1-βA, but not in B16F1-Ctrl tumors." (PMID 40064965, 2025).
cancer (21 papers, 2004 to 2025). A tumor composed of atypical neoplastic, often pleomorphic cells that invade other tissues. "This study identified KLK8 as a risk factor in LUSC and illustrated the associations between KLK8 and cancer immunity, suggesting the potentiality of KLK8 as a novel immune target in LUSC." (PMID 38273291, 2024). "While some immunosuppressive cells with cancer-promoting nature, like regulatory T cells (Tregs), M2 macrophages, and cancer-associated fibroblasts, displayed more intense infiltration in the KLK8 low expression group." (PMID 38273291, 2024). "In addition, we demonstrated the close associations between KLK8 and cancer immunity and showed the potentiality of KLK8 as a therapeutic target in LUSC." (PMID 38273291, 2024). "To assess the impact of Klk8 expression on cancer cells, we asked if its depletion by RNAi alters the proliferation of B16F1-Ctrl or -βA cells in 2D cultures, or their anchorage-independent survival in soft agar." (PMID 40064965, 2025). "More evidence about the interactions between KLK8 expression and cancer immunity warrants further exploration." (PMID 38273291, 2024). "Similar to our findings, several studies have confirmed that the upregulation of KLK8 was related to poorer cancer prognosis." (PMID 34395235, 2021). "As a secreted serine protease, KLK8 is known to mediate the proteolytic process of pro-EGF into mature EGF.EGF is known to activate PI3K/Akt/mTOR pathway in a variety of cancers." (PMID 34395235, 2021). "Meanwhile, accumulating evidence support the clinical utility of KLK8 as a biomarker for cancer survival and prognosis." (PMID 34395235, 2021). "Blood KLK8 levels have, furthermore, successfully been established as a biomarker for cancer diagnosis." (PMID 32414324, 2020). "The growth hormone somatotropin is another interesting natural substrate, as well as single-chain t-PA, which after activation by KLK8 activates plasmin, facilitating cancer cell invasion." (PMID 30013126, 2018). "Some genes representing the KEGG pathway “Pathways in cancer” (Pdgfra, Pdgfrb, Vegfa, PPP3ca, EphB2 and Prkcn) and the gene ontology term “regulation of transmission of nerve impulses” (Bdnf, Ngfb, Klk8 and Edn1) were also included." (PMID 22384097, 2012). "While very few EST clones were retrieved from the 14 EST cancer libraries (nine for KLK8, two for KLK3, and one for each of the rest), EST clones were much more detectable in normal libraries." (PMID 14710225, 2004). "In addition, we show that KLK8 expression in this and several other human cancers correlates with poor survival, further adding to its appeal as a future therapeutic target." (PMID 40064965, 2025). "However, the research about KLK8 was insufficient and contrary opinions exist on how KLK8 behaves in cancer." (PMID 38273291, 2024). "In addition, KLK8 expression is negatively correlated with cancer-killing effector cells, such as CD8 + T cells which repress cancer progression by the direct killing effects, and CD4+ Th1 cells which enhance the cytotoxic activity of CD8 + T cells." (PMID 38273291, 2024). "KLK8 has been considered a biological marker in several malignant tumours." (PMID 34552064, 2021). "Kallikrein-related peptidase 8 (KLK8) has potential clinical values in many cancers." (PMID 34395235, 2021). "In this study, we found that KLK8 expression in miR‐22 overexpression cells was significantly lower than another group, indicating that KLK8 may be a cancer‐promoting factor and negatively regulated by miR‐22." (PMID 31190355, 2019). "However, little was known about the significance of KLK8 in cancer immunotherapy before our study." (PMID 38273291, 2024). "Moreover, the GO analyses showed that the T cell activation, lymphocyte differentiation, leukocyte proliferation, and cytokine-cytokine receptor interaction were mainly enriched in the biological processes (BP), suggesting the close relationships between KLK8 and cancer immunity." (PMID 38273291, 2024).
cancer (continued). "However, some studies reported that KLK8 was a favorable prognostic marker in cancer." (PMID 38273291, 2024). "Among all the enriched pathways that were differentially expressed according to the diverse KLK8 expression levels in GSEA, epithelial−mesenchymal transition (EMT), a key step in enhancing cancer cell invasion and metastasis, attracted our attention." (PMID 34552064, 2021). "Using the KLK-CANMAP, a tool that includes several other cancer datasets, we again found the KLK6, KLK7, KLK8 and KLK10 cluster, with the exception of KLK11, which was upregulated in PDAC compared to normal pancreas tissues." (PMID 34439122, 2021). "The mRNA expression status of the KLK5, KLK6, KLK7, KLK8 and KLK9 has been extensively studied in cancer." (PMID 29229980, 2017). "To further validate the prognostic role of KLK8, we introduced a LUSC FFPE microarray (n = 190), of which the patients were retrospectively recruited in the Department of Thoracic Surgery, National cancer center (Beijing, China), into our study." (PMID 38273291, 2024). "KLK8 was significantly higher in ductal cells than in non-ductal cells, and in general, malignant tumors expressed higher levels of KLK8 compared to normal salivary gland tissue and benign tumors." (PMID 28855925, 2016).